IL6 (interleukin 6)
Diseases named in the same sentence as IL6 in open-access papers (continued):
Sharing a sentence is not in itself a finding about the gene and the disease.
tumor (continued). "By averaging z‐score expression levels per tumor, tumors with DDR mutation had lower expression levels of CTLA‐4, IFNG, TNF, FAS, and VTCN1, and higher expression levels of IL6, IL1B, and IL12A compared with the DDR wild‐type ones." (PMID 31991061, 2020). "Both, the pro- inflammatory cytokines TNF-α, IL-6 and IFNγ and anti-inflammatory cytokines IL-10 and IL-4 were enhanced in the serum compared to tumor bearing control, indicating a cytokine modulatory effect." (PMID 33415123, 2020). "In particular, in line with increased circulating IL6 in the mHCT116 tumor hosts, we also reported increased phosphorylated STAT3 levels in the skeletal muscle of mHCT116-bearing animals." (PMID 31915140, 2020). "Primary tumor-secreted IL-6 activated STAT3 in lymphatic endothelial cells, which then induced the expression of hypoxia-inducible factor 1 (HIF-1), vascular endothelial growth factor (VEGF), and chemokine ligand 5 (CCL5)." (PMID 33322216, 2020). "Evidence suggests that IL-6, a cytokine known for its pro-tumor behavior via JAK2/STAT3 signaling, can attract neutrophils within an immunosuppressed microenvironment." (PMID 31991796, 2020). "Our data suggest that up-regulation of Gal-9 expression in NPC cells promotes MDSC expansion depending on IL-1β and IL-6 induction from tumor cell and myeloid cell itself." (PMID 32632113, 2020). "IL-6 is recognized as the most critical bone marrow microenvironment factor supporting MM tumor growth." (PMID 32123307, 2020). "Compared to control subjects, chromogranin A level was higher in the CgA+ group (p = 0.0086), thrombopoietin (p = 0.0040) and chromogranin B (p = 0.0070) in the CgA− group, while interleukin-6 was high in both tumor groups (p ≤ 0.0090)." (PMID 33383764, 2020). "IL-6 is produced by multiple cell types located within the tumor microenvironment including tumor-infiltrating immune cells, stromal cells, and the tumor cells themselves." (PMID 33082817, 2020). "To further support the notion that the CD163-labelled M2 macrophages were activated, we showed expression of IL-10, TNF-α, TGF-β1 and IL-6 in all tumour tissues." (PMID 32070062, 2020). "Various cytokines (e.g., IL-6, IL-10, and IL-11) that are released into the microenvironment by tumor cells have also been shown to activate STAT3." (PMID 32188095, 2020). "In the tumor microenvironment, cytokines such as IL-6 regulate the interaction between CSCs and cancer cells." (PMID 32033472, 2020). "M1 activation, which is largely seen as tumor-inhibiting, is characterized by enhanced phagocytosis function as well as nitric oxide, IL-6, IL-12, and TNF production." (PMID 32708944, 2020). "Whereas fibroblasts with contact to tumor cells express αSMA and differentiate to myCAFs, peripheral cells produce IL–6 as iCAFs." (PMID 32775326, 2020). "Interleukin-6 (IL-6) is another protein whose expression is negatively regulated by apigenin and the reduced expression affects not only tumor proliferation, but also migration and invasiveness." (PMID 32110931, 2020). "Among various targets identified in cytokine array, IL-6 is a potent inflammatory cytokine that supports angiogenesis, modulation of inflammation, and cancer cell evasion from immune surveillance in the tumor microenvironment." (PMID 32005799, 2020). "While IL-6 and IL-8 both promote angiogenesis, tumor cell survival, chemoresistance, and migration; it was the high IL-6 serum levels which was associated with poor survival rate in advanced NSCLC." (PMID 32434541, 2020). "Inflammatory cytokines such as IL-6 are involved in tumor progression and metastasis, and experimental studies reported that inflammation can initiate cancer." (PMID 32637353, 2020). "In turn, osteoblasts produce factors that favour tumour growth, such as IGFs, chemokines, interleukin (IL)-6 and TGF-β." (PMID 32527062, 2020).
tumor (continued). "For instance, the induction of interleukin-6 (IL-6), IL-10, and CSF-1 contributes to the proliferation and invasion of tumor cells and thereby displays a pro-tumorigenic role." (PMID 33419318, 2020). "In the same study, an increase in inflammatory markers such as IL-1β, IL-6, iNOS, and TNFα was also observed in the tumor of voluntary runners." (PMID 33613297, 2020). "They exhibit pro-inflammatory and anti-tumor properties by releasing various types of pro-inflammatory cytokines and chemochines, such as Tumor Necrosis Factor (TNFα), Interleukin-6 (IL-6), Interleukin-1 Beta (IL-1β) and Nitric Oxide Synthase (INOs)." (PMID 32471272, 2020). "The expression level of tumor-associated macrophages (TAMs) and proinflammatory cytokines (TNF-α, IL-6) were evaluated by immunohistochemical (IHC)." (PMID 33643891, 2020). "Briefly, cells from CRC tumor tissue were cultured in the presence of LPS pre-treated or untreated with HDAC inhibitor or anti-IL-6." (PMID 31941522, 2020). "GC cell migration and invasion were promoted by the interaction of neutrophils with tumor cells through a pathway involving interleukin 6 (IL-6)." (PMID 32349701, 2020). "IL-6 mRNA was increased in the chemotherapy and chemo-radiotherapy tumors compared with matched adjacent normal and surgery alone tumor." (PMID 32814771, 2020). "In this study using the RM-1 tumor model, the concentrations of IL-6 and PGRN were significantly reduced with sequential treatment with anti-PD-1 and anti-Tim-3 antibodies." (PMID 31942188, 2020). "These approaches include targeting of CSCs with immunological methods such as CSC-DC vaccine, targeting the tumor microenvironment, anti-IL-6 mAb, inhibition of CSC-mediated immune-suppression, and blocking through anti-PD-1/PD-L1 mAbs." (PMID 32211043, 2020). "Another biologic rationale is the presence of tumor necrosis factor-alpha and interleukin-6 induced signaling, which can promote tumor growth." (PMID 33243216, 2020). "In this context, it was demonstrated that MDSCs elevated tumor growth and stemness in BC, and also produced IL-6 and nitric oxide (NO)." (PMID 32605277, 2020). "Chronic activation of the IL-6/JAK/STAT pathway in the tumor and its microenvironment produces a deregulated inflammatory cascade at cellular and systemic levels (increased C-reactive protein, neutrophil counts and decreased albumin)." (PMID 32145060, 2020). "IL6 mediated the cross talk between normal fibroblasts and the cancer cells, and promoted tumor cell migration through the STAT3 pathway." (PMID 31636361, 2020). "Increased IL6 production mediated by tumor-derived exosomes results in suppressed dendritic cell activity and attenuated immune response, resulting in enhanced tumor growth." (PMID 32547552, 2020). "The correct sentence should be: Tumor growth leads to the increased production of inflammatory cytokines and growth factors (mainly IL-1, IL-3, IL-6, IL-11, IL-23, and TNF-), and this perpetual process ensures immortality." (PMID 32293548, 2020). "IL-6 has pleiotropic effects on various cell types in the tumor microenvironment, which leads to the regulation of pro-oncogenic transcription factors NF-κB and STAT3." (PMID 32138303, 2020). "IL-6 released by TAMs induces the production of IL-10 by tumor cell via SATA3 signaling, which further enhances the IL-10 level within TME facilitating Tregs activation, survival, and accumulation." (PMID 32508809, 2020). "Within tumor microenvironments, IL-6/JAK/STAT3 signaling contributes to growth and metastasis of tumor cells by inhibiting the anti-tumor immune response." (PMID 32420905, 2020). "CAFs produce pro-inflammatory cytokines, such as COX-2, CXCL1, CCL5, CXCL11, and IL-6, which increase tumor cell proliferation and EMT." (PMID 33123161, 2020). "Meanwhile, IL-6-transformed macrophage CM promotes the viability of tumor cells, and addition PP VII inhibited this effect." (PMID 33288772, 2020).
tumor (continued). "Tumor metastasis is usually associated with abnormal expression of cytokines, especially CXCL12, VEGF, IL1β, and IL6, while CAFs can promote tumor growth and invasion via a plethora of active factors." (PMID 31636361, 2020). "IL-6 overexpression is present in numerous cancer types, leading to the dysregulation of a plethora of cellular activities that generally promote tumor progression." (PMID 32692308, 2020). "Several studies have shown that during the tumor initiation process, IL-6 is required in response to activated EGFR and K-RAS signaling." (PMID 32973222, 2020). "A recent study has found that both the activation of EGF-R pathways, as well as IL-6 trans signaling can be observed during tumor development, and both require ADAM17." (PMID 33143292, 2020). "IL-6 is a potent proinflammatory cytokine and participates in angiogenesis during wound healing, tumor progression, and the development of the cerebral vasculature." (PMID 33109684, 2020). "Oncogenic MAPK signaling results in the production of immunosuppressive factors (e.g., VEGF, IL-6 and IL-10), which inhibit the proliferation and activation status of tumor-specific T cells and DCs." (PMID 32290124, 2020). "Moreover, in human vestibular SC, immunohistochemical examination reveals an increasing of pro-inflammatory cytokines, including TGF-β1, IL-1β, and IL-6 that may promote growth of the neoplasm supported by the loss of Merlin protein with resulting enhance of NFKB transcriptome." (PMID 32244473, 2020). "Similar to IL-6, the CXCR2 ligand IL-8, also known as CXCL8, has been associated with inflammation, tumour growth and angiogenesis." (PMID 33116132, 2020). "Levels of IL-6 expression in the tumor environment, where it regulates several signaling pathways that promotes cancer progression, correlates with the prognosis in variety of cancer types." (PMID 32298379, 2020). "IL-1, IL-6, IL-8, and IL-18 are involved in the inflammatory process, IL-1 and IL-6 are involved in cell growth, metastasis, and tumor development." (PMID 32083131, 2020). "Many studies have shown that the IL-6 cytokine promotes tumor progression, as IL-6 is essential for inducting immune escape by upregulation of PD-L1 in a transcriptional or post-transcriptional manner." (PMID 32927431, 2020). "Sera of mice bearing A20 tumours were sampled at 120-h post treatment for analysis of cytokines, including IL-6, TNF-α and IFN-γ." (PMID 33014356, 2020). "The consequence is an inflammation, mediated mainly by IL-6, locally generating an immunosuppressive microenvironment responsible for the escape of tumor cells and their dissemination." (PMID 31936786, 2020). "In particular, interleukin-6 (IL-6) induces tumor cell invasiveness and increases the metastatic ability of tumor cells." (PMID 33322132, 2020). "Although many cell types produce IL-6, evidence suggests that the tumor microenvironment is an important source of this cytokine, which leads to increased systemic concentrations." (PMID 33233839, 2020). "In 60/86 HCCs, IL-6 expression in tumor tissues was found stronger than one in adjacent liver tissues." (PMID 31942180, 2020). "Inhibiting FAO can not only block the immunosuppressive function of MDSCs and allow T cells to kill tumor cells but also reduce the production of G-CSF, GM-CSF, and IL6 and promote the anti-tumor response." (PMID 33027968, 2020). "Once binding with its receptor, IL-6 activates various downstream pathways to regulating tumor formation and progression." (PMID 32134471, 2020). "IL-6 present in the tumor microenvironment induces the M2 phenotype differentiation in macrophages through the activation of the STAT3 pathway." (PMID 32268527, 2020). "Intratumoral treatment resulted in dose-dependent increases in IL-6 and TNFα in both tumor and serum at early time points, yet, the magnitude and duration of the response were substantially higher within tumors." (PMID 32483165, 2020).
tumor (continued). "Detection of IL-6, TNF-α, and TGF-β in blood of tumor-bearing nude mice showed that C-PC/CMC-CD55sp nanospheres induced an immune response that was associated with tumor growth inhibition." (PMID 32636744, 2020). "Our data support a functional link between activin A and IL‐6 signalling pathways and indicate that interference with activin A‐induced IL‐6 secretion from the tumour has therapeutic potential for cancer‐induced cachexia." (PMID 31436048, 2020). "Other mechanisms include the rearrangement of the tumor architecture (e.g., via MMPs), the induction of tumor cell proliferation and survival (e.g., through epidermal growth factor or IL-6), and the suppression of anti-cancer immunity (e.g., via PD-L1)." (PMID 33255584, 2020). "Other inflammatory mediators that upregulate PD-L1 expression in tumor and non-tumor cells include IL-6, prostaglandin E2 and HIF-1α." (PMID 32992658, 2020). "CD4+ and CD8+ T cells isolated from tumours of Fgf2LMW−/− mice had increased RNA expression of Il6, Il12, and Il17 compared with T cells isolated from WT mice." (PMID 32792542, 2020). "Analysed metabolites were adipokines (adiponectin, leptin, resistine), estradiol, interleukin 6 (IL-6), signalling pathways and tumour anti-oxidative response markers." (PMID 32472095, 2020). "New signaling pathways of interferon regulatory factors 1 (IRF-1) and 2 (IRF-2) and interleukin (IL)-1 family, IL-6, IL-11, IL-18, and interferons (IFNs) have been found within tumor microenvironments." (PMID 32887217, 2020). "Very similar findings were confirmed across several types of tumours, indicating a general role of IL-6 in cancer biology." (PMID 33114676, 2020). "It is reported that IL-6-mediated JAK/STAT3 pathway plays an important role in tumor proliferation, invasion and metastasis." (PMID 33153467, 2020). "One of the receptors responsible for activation of STAT3 is the receptor of interleukin-6 (IL-6), a pleiotropic cytokine highly produced in the tumour-baring host." (PMID 32779712, 2020). "Our results suggest that increased IL-6 levels promote FLS phenotype transition to tumour-like patterns that are responsible for the vicious cycle of cytokine and chemokine production." (PMID 33228785, 2020). "From Jean’s work, IL-6 and interferon pathways were activated in GNAS-mutated tumor tissues, suggesting that GNAS enzymatic activity is necessary for IL-6/STAT3 activation." (PMID 32123532, 2020). "Equally important, CAFs transformed under MSI-N1014 treatment resulted in a lower ability to promote tumor-sphere formation and 5-FU resistance, in part by reducing their secretion of IL-6 and VEGF." (PMID 32560222, 2020). "The authors showed that adrenaline activates β2-AR on NSCLC cells, which cooperatively signals with mutant EGFR to induce IL-6 expression through the tumor suppressor, liver kinase B1 (LKB1)." (PMID 33142779, 2020). "Evidence has shown that the IL-6 increase during CRS was specifically identified in sites at which CAR T cells colocalized with tumor tissue." (PMID 32665874, 2020). "Tumor exosomes inhibit bone marrow dendritic cell (DC) differentiation via the modulation of interleukin-6 (IL-6) expression." (PMID 33396739, 2020). "Of note, in this strain compared with WT mice, both the H and H+PH groups failed at rejecting the tumor even at day 21, strengthening the role of IL-6 as a major early contributor to KC survival and to the liver protection against tumor proliferation." (PMID 33178579, 2020). "In this context, IL-6 is a potential stimulatory cytokine found within the MB tumor microenvironment." (PMID 33279931, 2020). "By contrast, the addition of IL6 neutralizing antibodies to the co-culture system significantly inhibited tumor dissemination." (PMID 32308766, 2020). "In inflammatory and tumor microenvironment, TAMs can produce cytokines such as IL-6/IL-17/IL-23 to induce the tumor initiation and progression via the NF-κB or STAT3 signaling pathway." (PMID 33201893, 2020).
tumor (continued). "In the CAC milieu, IL-1β produced by neutrophils can induce intestinal mononuclear phagocytes (MPs) to produce IL-6, thereby promoting tumour formation." (PMID 32760201, 2020). "IL-6 is a well-known proangiogenic factor that promotes tumour cell proliferation, angiogenesis, and invasion." (PMID 32595725, 2020). "Circulating adiponectin presented an inverse correlation with gastrocnemius IL-6 and several tumour antioxidant factors (total glutathione, glutathione S-transferase and total COXs activities)." (PMID 32472095, 2020). "IL-6 has a two-sided effect on the development of tumors, both preventing tumor formation and promoting tumor progression." (PMID 33317597, 2020). "IL-6, a multifunctional cytokine, plays important roles in different types of cells including tumor cells." (PMID 32819324, 2020). "Changes in IL-6 concentration in the tumor microenvironment promote tumor invasion and metastasis and participate in recurrence." (PMID 32210805, 2020). "Of these cytokines, IL-6 remained significantly elevated in SS-31-treated C26 tumor-bearing mice compared to CON-SALINE and CON-SS-31 mice." (PMID 33014286, 2020). "IL-6 was shown to be overexpressed in GBM clinical samples and cell lines and IL-6 gene expression seems to correlate with the aggressiveness of the tumor." (PMID 32973662, 2020). "Beyond oxidative stress, myeloid cells are a crucial source of inflammatory cytokines, which can support the survival and proliferation of neoplastic cells (e.g., IL-6, IL-1, IL-23, IL-17A) or the activation of adaptive anti-tumor immunity (e.g., IL-12, IFNγ)." (PMID 32962159, 2020). "Multiple cell types located within the tumor microenvironment, including tumor-infiltrating immune and stromal cells and the tumor cells themselves, produce IL-6." (PMID 33082817, 2020). "It has been reported that in the tumor microenvironment, the IL-6/STAT3 signaling pathway plays an important role in the macrophage M2 polarization, and activation of the IL-6/STAT3 signaling pathway causes macrophages to polarize towards the M2 phenotype." (PMID 32904108, 2020). "Sonic hedgehog-activated stromal cells in the tumor microenvironment also secrete several immune mediators including interleukin (IL)-6 and IL-1β which in turn recruit myeloid-derived suppressor cells (MDSCs) to the tumor microenvironment." (PMID 35582227, 2020). "Our findings suggest that SLN-DTX inhibits tumor growth and prevents lung metastasis by reducing the production of IL-6 serum level, inducing apoptosis of the tumor cells and reduction of tumor cell proliferation and BCL-2 expression." (PMID 32164731, 2020). "Functionally, IL-4 and IL-6 increased tumor cell motility of BC cell lines, MCF-7 and MDA-MB 231, upon co-culture with hMDMs." (PMID 32784928, 2020). "IL-6 is one of the crucial regulators that help communicate between tumor cells and their microenvironment." (PMID 33536913, 2020). "The chronic presence of TNFα in tumors strongly enhances tumor progression; in parallel, IL-6 is also considered a strong tumor-promoting factor." (PMID 33585241, 2020). "CAFs isolated from a PDAC mouse model can be reversible from the αSMA-high and IL-6-producing states through modification of TGFβ and IL-1 tumor-secreted ligands, claiming for remarkable plasticity in fibroblast phenotypes." (PMID 32781778, 2020). "Specific inhibition of MDM2 in T-cell resistant tumor cells with high MDM2 expression decreases IL-6 expression and enhances T-cell-mediated killing regardless of changes in PD-L1 expression of the tumor cells." (PMID 32655895, 2020). "While several cytokines have well-established pro-tumor effects (e.g., IL-1, IL-4, IL-6) and can be produced by tumors directly in an autocrine manner, not all cytokines contribute toward pro-tumor processes." (PMID 33597950, 2020).